Y_RNA (Y RNA )
Gene: Miscellaneous RNA gene on chromosome 20 (34,384,165 to 34,384,265, reverse strand). Ensembl gene ENSG00000201498.
Homologues: Orthologues: chimpanzee Y_RNA (95% identical), macaque Y_RNA (93% identical), dog Y_RNA (83% identical), pig Y_RNA (83% identical). Paralogues in human: Y_RNA (89% identical), RNY3 (88% identical), RNY3P1 (87% identical), Y_RNA (87% identical), Y_RNA (86% identical), Y_RNA (85% identical), RNY3P16 (84% identical), Y_RNA (84% identical), Y_RNA (83% identical), RNY3P14 (82% identical), RNY3P4 (82% identical), Y_RNA (82% identical), and 95 more.